ACTN4 (actinin alpha 4)
Description:
F-actin cross-linking protein which is thought to anchor actin to a variety of intracellular structures. This is a bundling protein (Probable). Probably involved in vesicular trafficking via its association with the CART complex. The CART complex is necessary for efficient transferrin receptor recycling but not for EGFR degradation. Involved in tight junction assembly in epithelial cells probably through interaction with MICALL2. Links MICALL2 to the actin cytoskeleton and recruits it to the tight junctions (By similarity). May also function as a transcriptional coactivator, stimulating transcription mediated by the nuclear hormone receptors PPARG and RARA. Association with IGSF8 regulates the immune synapse formation and is required for efficient T-cell activation.
Synonyms: ACTININ-4; FSGS; FSGS1
Tractability: Antibody: its Gene Ontology location is reachable by antibodies, with high confidence. PROTAC: ubiquitination databases record sites on it; its protein half-life has been measured.
Gene: Protein-coding gene on chromosome 19 (38,647,605 to 38,731,589, forward strand). Ensembl gene ENSG00000130402.
Subcellular location: Nucleus; Cytoplasm; Cell junction; Cytoplasm, cytoskeleton, stress fiber; Cytoplasm, perinuclear region
Subcellular location (Human Protein Atlas): Actin filaments; Focal adhesion sites; Cytosol; Primary cilium; Primary cilium transition zone
Pathways (Reactome):
Cell-Cell communication: Nephrin family interactions
Hemostasis: Platelet degranulation
Gene Ontology:
Molecular function: actin filament binding; chromatin DNA binding; nuclear receptor binding; nuclear retinoic acid receptor binding; nucleoside binding; protein binding; protein homodimerization activity; RNA binding; RNA polymerase II transcription regulatory region sequence-specific DNA binding; transcription coactivator activity; transmembrane transporter binding; actin binding; integrin binding; calcium ion binding; identical protein binding
Biological process: negative regulation of substrate adhesion-dependent cell spreading; peroxisome proliferator activated receptor signaling pathway; positive regulation of cell migration; positive regulation of non-canonical NF-kappaB signal transduction; positive regulation of transcription by RNA polymerase II; retinoic acid receptor signaling pathway; tumor necrosis factor-mediated signaling pathway; vesicle transport along actin filament; actin cytoskeleton organization; muscle cell development; positive regulation of sodium:proton antiporter activity; regulation of apoptotic process
Cellular component: actin cytoskeleton; cytoplasm; extracellular exosome; extracellular region; focal adhesion; nucleus; perinuclear region of cytoplasm; postsynaptic actin cytoskeleton; protein-containing complex; ribonucleoprotein complex; anchoring junction; cell junction; cortical actin cytoskeleton; plasma membrane; platelet alpha granule lumen; pseudopodium; Z disc; stress fiber
Genetic constraint (gnomAD): Loss-of-function variants: 18 observed, 112.31 expected, observed/expected ratio (o/e) 0.16, 90% interval 0.11 to 0.24. The upper end of that interval is the gene's LOEUF score, 0.24, which puts it in group 1 of 6, group 1 being the genes least tolerant of losing a copy. Missense variants: 722 observed, 1,279.8 expected, observed/expected ratio (o/e) 0.56, 90% interval 0.53 to 0.6. Synonymous variants: 515 observed, 515.87 expected, observed/expected ratio (o/e) 1, 90% interval 0.93 to 1.07.
Homologues: Orthologues: chimpanzee ACTN4 (100% identical), macaque ACTN4 (100% identical), pig ACTN4 (99% identical), guinea pig ACTN4 (99% identical), mouse Actn4 (99% identical), rat Actn4 (98% identical), tropical clawed frog actn4 (89% identical), rabbit ACTN4 (67% identical). Paralogues in human: ACTN1 (84% identical), ACTN2 (76% identical), ACTN3 (72% identical), SPTBN1 (32% identical), SPTBN2 (31% identical), SPTBN4 (31% identical), SPTB (31% identical), PLEC (27% identical), DST (26% identical), MACF1 (26% identical), SPTBN5 (26% identical), SYNE1 (24% identical), and 24 more.
Diseases named in the same sentence as ACTN4 in open-access papers:
ACTN4 is named in the same sentence as 131 diseases in open-access papers, as found by Europe PMC text mining. Sharing a sentence is not in itself a finding about the gene and the disease. The quoted sentences say what the papers report.
breast cancer (27 papers, 2014 to 2025). A primary or metastatic malignant neoplasm involving the breast. "To date, ABPs that have been implicated in breast cancer cell migration, invasion, and growth include α-actinin 4 (ACTN4), actin filament-associated protein (AFAP-110), coronin-like actin-binding protein 1C (CORO1C), girdin, and anillin (ANLN)." (PMID 34194957, 2021). "Then we focused on a novel circRNA circACTN4 (hsa_circ_0050900) from ACTN4 gene and investigated its biological functions as well as the underlying molecular mechanisms in the breast cancer development." (PMID 34116677, 2021). "In the Japanese cohort, multivariate analysis revealed that a copy number increase (CNI) of ACTN4 was an independent factor associated with high risks of recurrence (P = 0.01; hazard ratio (HR), 2.95) and breast cancer death (P = 0.014; HR, 4.27)." (PMID 32265507, 2020). "A proteomic search for protein markers associated with estrogen receptor (ER) status, tumor grade and lymph node status in a set of breast cancer samples revealed an association between the ACTN4 protein and the lymph node status in high grade tumors." (PMID 31766144, 2019). "Overall, ACTN4 promotes breast cancer progression and metastasis, and is an independent prognostic marker associated with the poor clinical outcome in breast cancer patients." (PMID 29197410, 2017). "ACTN4 is often associated with the occurrence and development of various tissue types of tumors, such as colon cancer, breast cancer, pancreatic cancer and ovarian cancer, which proved that the high expression of ACTN4 is closely related to the metastatic and invasive ability of tumors." (PMID 36742137, 2023). "We have hypothesised that an increase in the copy number of the ACTN4 gene might also identify luminal B-like/HER2-negative breast cancers with a high risk of recurrence." (PMID 32265507, 2020). "Univariate analysis revealed that histological grade (P = 0.0004; HR, 10.16; 95% CI: 2.81–37.1), nuclear grade (P = 0.002; HR, 7.52; 95% CI: 2.07–27.34), and ACTN4 copy number status (P = 0.0035; HR, 5.78; 95% CI: 1.78–18.77) were significantly associated with breast cancer-associated death." (PMID 32265507, 2020). "al., 7 found that ACTN4 was associated with poor prognosis in breast cancer patients, much laboratory and clinical work has been done to illustrate the relationship between actinins and solidary tumors, but little attention had been paid to that between actinins and hematological disorders." (PMID 31413748, 2019). "Both contribute to podosome formation, with ACTN4 playing a key role in extracellular matrix degradation mediated by podosomes in breast cancer cells." (PMID 40821124, 2025). "Wang and colleagues (2017) sought to determine the role and regulation of ACTN4 expression in human breast cancer metastasis under ellagic acid (EA)-based therapy." (PMID 39061201, 2024). "Knockout of the ACTN4 gene significantly reduced the expression of estrogen receptor-α in MCF-7 breast cancer cells." (PMID 34194957, 2021). "The β-catenin stabilization is responsible for CSC features in breast cancer and ACTN4 functions as upstream mediator." (PMID 34769099, 2021). "Results suggest that the co-overexpression of circACTN4 and ACTN4 cooperatively promotes the progression of breast cancer." (PMID 34116677, 2021). "The ellagic acid administration (0–50 μM) reduces ACTN4 expression to inhibit β-catenin signaling in CSCs, impairing breast cancer progression." (PMID 34769099, 2021). "According to early studies, ACTN4 is thought to be a component of the motile system of breast cancer cells and is strongly expressed in the nucleus, suggesting that ACTN4 is involved in breast cancer tumorigenesis emergence." (PMID 34571787, 2021). "shACTN4 suppresses the Akt/GSK-3β/β-catenin signaling, and ACTN4 interacts with β-catenin in breast cancer stem cells." (PMID 33363146, 2020).
breast cancer (continued). "The metastatic ability of ACTN4 in colorectal cancer, breast cancer, ovarian cancer, pancreatic cancer, salivary gland cancer, and prostate cancer is related to the malignant phenotype." (PMID 32670437, 2020). "ACTN4 functions as a coactivator of oncogenic transcription factors in cervical, lung, colorectal, and breast cancers." (PMID 33363146, 2020). "Anti-metastatic activity of ellagic acid is inhibition of the ACTN4 gene, which is responsible for breast cancer stem cell self-renewal and their metastatic abilities, and consequently for poor survival of breast cancer patients." (PMID 32397337, 2020). "Univariate Cox regression analysis showed that ACTN4 CNI was the sole factor significantly associated with high risks of recurrence (P = 0.04; HR, 2.73; 95% CI 1.03–7.24) and breast cancer death (P = 0.016; HR, 4.01; 95% CI: 1.29–12.49)." (PMID 32265507, 2020). "Copy number analysis of a single gene, ACTN4, can identify early-stage luminal breast cancer patients with a distinct outcome." (PMID 32265507, 2020). "In particular, ellagic acid (MOL005858) has been shown to restrain pulmonary metastasis mainly via targeting ACTN4 and subsequently destroying β-catenin stabilization in breast cancer stem cells." (PMID 33381039, 2020). "In a more recent study, it was further demonstrated that one of the components of SA, namely ellagic acid, limited breast cancer stem cell metastasis by directly targeting ACTN4 and subsequently promoting β-catenin destabilization." (PMID 33381039, 2020). "In breast cancer, the knockdown of ACTN4 can reduce the expression of ERa target genes and cell proliferation." (PMID 32670437, 2020). "Recent researches have reported that the expression of ACTN4 is significantly elevated in multiple cancers, including breast cancer, pancreatic cancer, ovarian cancer, and lung cancer." (PMID 32855746, 2020). "In late-stage metastatic breast cancers, the ACTN4 levels decrease in the nucleus, as is observed in high-grade cancerous prostate samples, suggesting that ACTN4 is possibly deregulated in advanced stage cancers." (PMID 32326308, 2020). "For instance, ellagic acid disrupts the ACTN4 interaction with β-catenin, which subsequently leads to the suppression of breast cancer cell proliferation as well as ablating tumor growth and metastasis in an MMTV-PyMT breast cancer mouse model." (PMID 31766144, 2019). "An augmented migratory potential was reported for a large number of ACTN4-over-expressing cells, including osteosarcoma, colorectal cancer, squamous carcinoma, breast cancer, lung cancer, and others." (PMID 31766144, 2019). "Since ACTN4's prognostic value in breast cancer was established, many works have been done to investigate the role of actinins in cancer prognostication and tumorigenesis." (PMID 31413748, 2019). "Another recent study showed that the mRNA level of ACTN4 was significantly elevated in breast cancers of the metastatic phenotype, and in triple-negative breast cancer tumors, lacking ER, PR, and HER2." (PMID 31766144, 2019). "The current study sought to determine the role and regulation of ACTN4 expression in human breast cancer metastasis and EA-based therapy." (PMID 29197410, 2017). "EA inhibited breast cancer growth and metastasis via directly targeting ACTN4 in vitro and in vivo, and was accompanied by a limited CSC population." (PMID 29197410, 2017). "TNBC phenotypes, which are usually enriched for CD44+/CD24− CSCs, also displayed higher ACTN4 expression than other breast cancer subtypes." (PMID 29197410, 2017). "The reduced expression of ACTN4 was further confirmed at protein levels in EA–treated breast cancer cell lines." (PMID 29197410, 2017). "Our findings would not only facilitate present understanding on the critical role of ACTN4 in breast CSCs metastasis, but also benefit for designing potentially more effective therapeutic strategies against breast cancer." (PMID 29197410, 2017).
breast cancer (continued). "In conclusion, our study not only identified ACTN4 as the direct target of EA, but it also highlighted its significant role in mediating breast cancer metastasis and CSCs’ properties." (PMID 29197410, 2017). "Immunoblotting and real-time PCR analysis revealed that the enhanced expression of ACTN4 was observed in several basal-like breast cancer cell lines (MDA-MB-231, BT-549, and HCC1937) compared with the normal mammary cell line MCF-10A." (PMID 29197410, 2017). "In the present study, we demonstrated at least 4 lines of evidence supporting the crucial roles of ACTN4 in facilitating CSCs and metastasis in breast cancer." (PMID 29197410, 2017). "Further validation suggested that EA administration significantly suppressed ACTN4 expression in vitro and in vivo in the breast cancer model, accompanied by CSC suppressive effects." (PMID 29197410, 2017). "It is promising to develop ACTN4 targeting strategies to predict or inhibit breast cancer metastasis in the future, especially for the basal-like phenotypes." (PMID 29197410, 2017). "Proliferation analysis revealed that ACTN4 overexpression enhanced breast cancer cell number, and effectively restored the inhibition effects of EA on breast cancer cells." (PMID 29197410, 2017). "The mechanisms by which ACTN4 regulate TRAIL-induced apoptosis in breast cancer cells will require further investigation." (PMID 24745479, 2014). "Overall, this suggests that BCL2L1, BIRC2, and ACTN4 are potentially major regulators of TRAIL-induced caspase-3/7 in breast cancer and that their LOF has the potential to overcome resistance to TRAIL-induced cytotoxicity." (PMID 24745479, 2014). "EA inhibited breast cancer growth and metastasis by directly targeting ACTN4 in vitro and in vivo." (PMID 39061201, 2024). "Moreover, EA effectively impeded the growth and metastasis of breast cancer by directly targeting ACTN4 (Alpha-actinin-4)." (PMID 38002335, 2023). "Taken together, these findings suggest that ACTN4 could potentially serve as a critical target for EA treatment, particularly in the context of breast cancer stem cell-related metastasis." (PMID 38002335, 2023). "Moreover, ACTN4 has been revealed to function as a nuclear receptor coactivator in Breast Cancer (BC)." (PMID 34546849, 2021). "Silencing ACTN4 impairs growth, migration and colony formation capacities in breast cancer." (PMID 34769099, 2021). "This compound could be applicable for prevention of recurrence in breast cancer patients with ACTN4 CNI." (PMID 32265507, 2020). "In addition, ACTN4 knockdown reduces ERα target gene expression and decreases the proliferation of breast cancer cells." (PMID 33363146, 2020). "In addition, ACTN4 is found in the membrane ruffles, and the inhibition of PI3 kinase (PI3K) promotes ACTN4 nuclear translocation in breast cancer and several cancer cell lines." (PMID 30680066, 2018). "Also, significant differences in ACTN4 expression are suggested to play a role in chemoresistance in breast cancer; either its up-regulation or down-regulation varies depending on the chemotherapeutic." (PMID 29443940, 2018). "Given that ACTN4 might be a bridge connecting CSCs and metastasis function in breast cancer, particularly for the basal-like populations, we then investigated the expression of ACTN4 in ALDEFLOUR-positive cells or CD44+/CD24− populations." (PMID 29197410, 2017). "Taken together, our results showed that EA could suppress the ACTN4 expression both in vitro and in vivo, suggesting that ACTN4 might be a critical contributor to breast cancer metastasis." (PMID 29197410, 2017). "In addition, some studies have shown that ACTN4 can also promote the progression of breast cancer." (PMID 34116677, 2021). "Importantly, the ACTN4/β-catenin axis was shown to promote CSC traits in breast cancer cell lines." (PMID 31766144, 2019).
breast cancer (continued). "The correlation between ACTN4 expression and tumour grade, tumour progression, and metastasis were reported for various human cancers, including osteosarcoma, melanoma, leukemia, prostate cancer, bladder cancer, lymphoma, pancreatic cancer, breast cancer, and gastric cancer." (PMID 29443940, 2018). "The other nuclear receptor co-activator related to invasion is actin-binding protein, actinin α 4 (ACTN4), which has been shown to promote the proliferation of MCF-7 breast cancer cells." (PMID 32326308, 2020). "A recent study demonstrated that serum ACTN4 levels were dramatically elevated in patients with breast cancer when compared to healthy controls, and serum ACTN4 may be an effective clinical indicator for diagnosing or predicting the clinical outcomes of breast cancer patients." (PMID 32855746, 2020). "ACTN4 knockdown decreases the activation of Akt and GSK-3β, and it reduces cell motility in breast cancer." (PMID 33363146, 2020). "As shown in representative images, ACTN4 was slightly expressed in the normal mammary tissues, whereas its expression was gradually increased in stages I–III breast cancer." (PMID 29197410, 2017). "Of note, ACTN4 can serve as a scaffold to promote AKT activation, and it has been shown to interact with NF-κB in breast cancer cells (although the significance of this latter interaction is not known)." (PMID 24745479, 2014). "Univariate analysis revealed that histological grade (P = 0.006; HR, 2.52; 95% confidence interval [CI]: 1.3–4.86), nuclear grade (P = 0.005, HR, 2.57; 95% CI: 1.33–4.94), and ACTN4 FISH (P = 0.002, HR, 3.62; 95% CI: 1.59–8.27) were significantly correlated with recurrence of breast cancer." (PMID 32265507, 2020). "In the present study, we examined the feasibility of ACTN4 copy number status as a novel single-gene assay for stratification of node-negative luminal breast cancer." (PMID 32265507, 2020). "To determine the ACTN4 tissue distribution and expression pattern in human breast tumors, we investigated the expression of the ACTN4 protein in a TMA containing 60 primary breast cancers and paired tumor adjacent normal (TAN) mammary tissues." (PMID 29197410, 2017). "However, few studies have revealed the mechanisms of ACTN4-mediated CSC activities and tumor metastasis in breast cancer." (PMID 29197410, 2017). "Thus, it is reasonable that combined utilization of ACTN4 and CD44+/CD24− markers might be more sufficient to isolate metastatic cells with CSC properties in breast cancer." (PMID 29197410, 2017). "Moreover, subcutaneous injection of ACTN4-expressing CD44+/CD24− cells resulted in an increased incidence of tumor formation, even when only 1000 cells were implanted, further verifying the tumorigenic significance of ACTN4 on breast cancer." (PMID 29197410, 2017). "Nuclear localization of the protein was seen in different tumors, and recruitment of ACTN4 to the pS2 promotor, an estrogen receptor (ER) target in the ER-positive breast cancer cell line MCF7, suggested that ACTN4 may play a role in E2-mediated regulation of breast cancer proliferation." (PMID 29143101, 2018).